INS (insulin)
Diseases named in the same sentence as INS in open-access papers (continued):
Sharing a sentence is not in itself a finding about the gene and the disease.
diabetes (continued). "The changes in the normal pattern of plasma insulin oscillations are an early marker of insulin resistance and diabetes mellitus and can be found in diabetic animal models, such as ob/ob mice and ZDF rats, as well as in diabetic patients and even their relatives." (PMID 33833686, 2021). "The effects of garlic oil and diallyl disulfide on blood glucose regulation and renal function showed that the administration of garlic oil (100 mg/kg) and DADS (40 or 80 mg/kg) until 16 weeks after the induction of diabetes stimulated insulin secretion in STZ-diabetic rats." (PMID 34867384, 2021). "Since its discovery in 1921, insulin has become the mainstay of diabetes management." (PMID 34774054, 2021). "Inosine is a potent stimulator of insulin secretion from isolated mouse islet cells, but its relation with diabetes development in humans remains unknown." (PMID 35069433, 2021). "Through the analysis of the role of S1P in the pathogenesis of diabetes, we found that S1P and its related molecules can increase the tissue's sensitivity to insulin, protect islet β cells, and regulate appetite, thus having the potential to be developed as drugs for T2DM." (PMID 34751249, 2021). "Inadequate insulin secretion in response to glucose is the main and early pathogenesis of diabetes." (PMID 34556670, 2021). "In conclusion, we found that ELO water raised arterial oxygen levels in animal models, improved cellular oxygenation and altered markers of mitochondrial function, and is an effective adjuvant therapy even in people with longstanding diabetes already on insulin." (PMID 34260650, 2021). "Metabolic alkalosis induced by ingestion of alkaline water may enhance insulin sensitivity in type 1 diabetes mellitus." (PMID 34084477, 2021). "An imbalance in relative MR–GR activation, with a shift towards increased MR-dependent activation due to an elevated cortisol nadir is hypothesized to be a pathophysiological mechanism for metabolic disruption in obesity, insulin resistance, and diabetes." (PMID 34436424, 2021). "The precise control of insulin secretion in β-cells is important to maintain blood glucose stability; insulin secretion disorders may lead to chronic hyperglycemia and diabetes." (PMID 33897780, 2021). "In this mini-review, we highlight the importance of such chemical glycosylation methods for improving the biophysical properties of naturally non-glycosylated peptides as applied to the therapeutically essential insulin and related peptides that are used in the treatment of diabetes." (PMID 33912539, 2021). "Diabetes only manifests if there is an additional disruption of pancreatic insulin secretion." (PMID 34591793, 2021). "Consequently, patients taking insulin prior to bariatric surgery are skeptical about having diabetes resolution." (PMID 34873559, 2021). "Sociodemographic and clinical characteristics of patients with diabetes on insulin therapy." (PMID 34704954, 2021). "Children and adolescents diagnosed with diabetes may initially be treated with insulin, and this regimen often continues even after the stabilization of glycemia." (PMID 33604390, 2021). "This difference could be explained by longer diabetes duration, the criteria of insulin treatment and a potentially higher incidence of cardiac autonomic neuropathy in the present study." (PMID 34085953, 2021). "Therefore, this insulin-loaded chitosan-Dz13Scr NP was presented as a potential drug delivery system for the management of diabetes mellitus." (PMID 34502560, 2021). "Thus, an achievement of a reasonable glycemic control through oral hypoglycemic agents (OHAs), insulin administration, or dietary management would alleviate the GI symptoms in diabetes." (PMID 34712528, 2021). "Intriguingly, the potential roles of insulin in the pathogenesis and treatment of some neurological diseases, including depression, cognitive decline, and Alzheimer's disease (AD), have expanded the brain insulin signaling research field beyond the confines of diabetes." (PMID 33845179, 2021).
diabetes (continued). "As rates of diabetes continue to rise, the cost, storage, and administration requirements for insulin have proven to be of increasing concern, particularly in developing countries where these storage requirements may not be feasible." (PMID 34071182, 2021). "Insulin sensitivity is greater in women, who are characterized by higher capacities for insulin secretion and incretin responses than men; however, if glucose tolerance is present, both gender progress toward diabetes." (PMID 34829598, 2021). "The possibility of obtaining a large number of mature, insulin-producing cells from hiPSC could provide an unlimited source of surrogate β-cells to replace damaged cells in diabetic patients of all types of diabetes." (PMID 34571911, 2021). "These health system factors can also have an impact on the overall cost of diabetes management, with individuals needing to pay for travel from their home to a facility where insulin is present or only being able to access this medicine in the private sector at higher prices." (PMID 33483763, 2021). "Diabetes is generally divided into four categories: type 1 diabetes (T1DM) (autoimmune β-cell destruction usually accompanied by absolute insulin deficiency), type 2 diabetes (T2DM) (a gradual decrease in β-cell insulin secretion), gestational diabetes, and specific types of diabetes." (PMID 33510802, 2021). "For example, the DIGAMI study demonstrated that intensive insulin therapy reduced all-cause mortality in AMI patients with stress hyperglycemia irrespective of the previous diabetes status." (PMID 34355031, 2021). "Patients aged 31-35 years, those with a duration of diabetes (6-10 years), those who are on insulin therapy, and those who have reported hospital admission for hypoglycaemic episodes in the previous six months were more likely to have poor mental wellbeing status compared to others (p<0.05)." (PMID 34646639, 2021). "The word “diabetes” defines a diverse array of chronic metabolic conditions, all characterized by hyperglycemia in absence of treatment, resulting from deficient insulin secretion, insulin action, or both." (PMID 34281162, 2021). "Type 2 diabetes mellitus (T2DM) is one of the most common chronic metabolic diseases associated with obesity, which is characterized by the resistance to insulin and inability to produce insulin by pancreatic β-cells." (PMID 34829881, 2021). "Although intra islet paracrine signaling between the different endocrine cell types is crucial for fine-tuned insulin secretion, different reports have shown that diabetes can be rescued with nearly pure populations of islet beta cells with different efficiency." (PMID 33828531, 2021). "Residual insulin secretion in diabetes has clinical importance regarding glycaemia." (PMID 34083567, 2021). "We investigated the effects of a lemon extract (LE), containing ≥20.0% total flavanones and ≥1.0% total hydroxycinnamic acids, on insulin signaling in murine 3T3-L1 adipocytes treated with TNF-α, which was used to mimic in vitro the insulin resistance condition that characterizes diabetes mellitus." (PMID 34361563, 2021). "In some ways this may be more convenient for individuals with diabetes given the frequent visits required for insulin titration throughout pregnancy due to the dynamic changes in glucose metabolism and insulin resistance as pregnancy progresses." (PMID 33512267, 2021). "This type of system can discharge sufficient insulin during hyperglycemia and self-adjust to release a smaller insulin dose during normoglycemia; this is desirable for improving the quality of life of patients with diabetes." (PMID 35056918, 2021). "These last two groups could affect the release of gut hormones to regulate insulin release, reverse IR, and achieve diabetes control." (PMID 33917044, 2021).
diabetes (continued). "NOD mice lacking Ins2 gene develop accelerated diabetes, ascribed to loss of central tolerance to insulin peptides; however, development of insulin autoantibodies (IAA) in Ins2 -/- mice suggests that immune responses against PIns1 epitopes are intact." (PMID 33841427, 2021). "By highlighting the importance of GIGYF1 and GRB adapter proteins in modulating insulin signaling this finding may lead to new therapeutic approaches for the treatment of diabetes." (PMID 34732801, 2021). "The CANVAS Program had a higher proportion of insulin use at baseline compared with other major trials, suggesting a higher proportion of participants with more complex type 2 diabetes mellitus, yet still reported favourable outcomes in this subgroup of participants." (PMID 34448033, 2021). "In addition, heterogeneity in the incidence of diabetes has been described for this rat model and variation in insulin treatment responses has been reported for similar animal models despite the same genetic background." (PMID 33557206, 2021). "Diabetes is characterized by β-cell failure, which can be auto-immune due to β-cell destruction, or by a progressive impairment of β-cells function that leads to insufficient insulin secretion." (PMID 34444990, 2021). "The healthcare provider can download the data from the pen, along with CGM data, and this can aid in improving the management of the patient’s diabetes by informing adjustment of the insulin:carbohydrate ratio at each meal, the correction factor, and target range." (PMID 34184589, 2021). "Chronically persistent hyperglycemia promotes the occurrence of oxidative stress, which entails a number of pathological changes in the body, including impaired insulin secretion or excessive apoptosis of β cells of the pancreatic islets and in the long run leads to overt manifestation of diabetes." (PMID 34576213, 2021). "SphK1(−/−) mice developed diabetes and had reduced insulin levels compared with the WT mice." (PMID 34943862, 2021). "Diabetes mellitus is a metabolic disorder characterized by persistent hyperglycemia in the bloodstream as a result of the disabled action and/or failure in production of the hormone insulin, which has as function to promote glucose entry into cells." (PMID 34366888, 2021). "In addition to insulin therapy, one patient in each group was also receiving metformin for diabetes treatment." (PMID 34064218, 2021). "In addition, alterations of the insulin pathway also result in diabetes via insulin insufficiency (type I diabetes) or insulin resistance and pancreatic β-cell dysfunction (type II diabetes)." (PMID 33484713, 2021). "The clinical model therefore included pre-intervention HbA1c, use of insulin, number of non-insulin diabetes medications and percent weight loss at 2 years." (PMID 33627633, 2021). "However, metabolic overload stimulates ROS overproduction which impairs insulin secretion and insulin action during diabetes." (PMID 34542937, 2021). "Gender (p-value for interaction = 0.03), BMI (p-value for interaction = 0.004), insulin treatment (p-value for interaction<0.001), family history of diabetes (p-value for interaction<0.001) and CVD (p-value for interaction<0.001) were all significant modifiers for associations between PA and RPC." (PMID 33444338, 2021). "Indeed, a higher production of amylase induces an early degradation of oral starch, ameliorating also the blood glycemic and insulin profile, as well as the disease states of metabolic syndrome, diabetes and obesity." (PMID 34444230, 2021). "Obviously, insulin is an integral part of the treatment of diabetes." (PMID 34762125, 2021). "Studies analyzing genome-wide profiles of DNA methylation in human islets from healthy and T2D individuals show specific changes in the islet methylome in diabetes, resulting in the alteration of expression of genes that are critical for insulin secretion, β-cell adaptation, and survival." (PMID 33239359, 2021).
diabetes (continued). "Insulin pump therapy was implemented at diabetes onset which was rare at that time." (PMID 34727899, 2021). "Furthermore, the interpretation of results on long duration type 2 diabetes mellitus when low fasting insulin was ≤5 μU/mL and fasting glucose was <81 mg/dL or 4.5 mmol/L was not valid." (PMID 34442147, 2021). "Indeed, this systematic review brings together articles demonstrating the impact of HBOT in lowering blood glucose and improving insulin sensitivity in people with type 2 diabetes mellitus." (PMID 34684171, 2021). "The increased glucagon/insulin ratio is responsible for increased lipolysis and upregulated ketone body production (β-hydroxybutyrate, acetoacetate), which may lead to ketoacidosis." (PMID 34068655, 2021). "Not all instances of monogenic diabetes secondary to reduced insulin secretion are associated with lower birthweight." (PMID 33569631, 2021). "Generally, high-fat diet (HFD)-induced insulin resistance (IR) is caused by the reduction of GLUT4 translocation through a defective insulin signaling pathway, and in type 1 diabetes mellitus (T1DM) patients, the translocation and activation of GLUT4 does not occur due a lack of insulin production." (PMID 33660027, 2021). "In all CF patients with diabetes and prediabetes treated with insulin analysis of glucose metrics with CGM may be useful for monitoring insulin treatment, -Conditional in Favor-." (PMID 34017312, 2021). "For the management of diabetes, the overall study population was on treatment with insulin analogs." (PMID 34575228, 2021). "In addition, persistent hyperglycemia due to diabetes induces IL-6- and IL-1β-mediated dysfunction of insulin secretion." (PMID 34836432, 2021). "In an experimental rat model of diabetes, Q exerted protective effects through regulating inflammatory responses (particularly those resulting from viral infection), promoting pancreatic islet regeneration, and increasing insulin release." (PMID 33661932, 2021). "Dietary factors are likely to play the major part in the pathogenesis of type 2 diabetes mellitus, but mercury in pancreatic insulin-producing cells could contribute to diabetes by inhibiting insulin secretion." (PMID 34408264, 2021). "Therefore, we analyzed fat tissue samples from long-term diabetic (2 years) INSC94Y transgenic pigs, a model for mutant INS gene induced diabetes of youth (MIDY), and wildtype (WT) littermates." (PMID 34888323, 2021). "They believed that high blood pressure can be controlled by just taking a pill, while diabetes is painful and complicated, as one needs to take insulin shots and may eventually suffer from limb amputation." (PMID 33572878, 2021). "Insulin, also classified as an injection drug, is mainly used for patients with severe diabetes." (PMID 34663286, 2021). "Therefore, it was concluded that replenishment of insulin-producing pancreatic β cells is crucial for treating diabetes and preventing its complications." (PMID 34054538, 2021). "It is commonly thought that high-insulin plasma levels in pre-diabetic to type 2 diabetes mellitus (T2DM) patients contributes to AD development, with increasing evidence suggesting an exacerbation of cognitive impairment, neuroinflammation, Aβ aggregation, and tau hyperphosphorylation in AD." (PMID 34065168, 2021). "Another study found a higher severity of depression among patients with diabetes who use insulin." (PMID 33803134, 2021). "Diabetes is a chronic disease that occurs either when the pancreas does not produce enough insulin (a hormone that regulates blood sugar) or when the body cannot effectively use the insulin it produces." (PMID 34831299, 2021). "It has recently been observed that the eradication of HCV (hepatitis C virus) infection with direct-acting antiviral therapy, probably through the elimination of chronic inflammation due to the infection, leads to a reduction in insulin-resistance as well as both the onset of diabetes." (PMID 34011282, 2021).
diabetes (continued). "One of the reasons for recurrent hypoglycemia in patients with diabetes for more than 5 years could be “unrecognized” chronic kidney disease, as the kidney is the site for the degradation of insulin." (PMID 34690922, 2021). "When insulin is unable to perform its function, blood glucose level rises above the normal levels and the condition called hyperglycemia takes place, which is known as diabetes mellitus." (PMID 34540481, 2021). "Studies have shown that dietary patterns with high insulin secretion ability such as the western diet in individuals with an unhealthy lifestyle could due to the developing incidence of diabetes and other chronic diseases." (PMID 33892738, 2021). "Furthermore, we also found that restoring insulin signaling in multidendritic sensory neurons can block diabetes-induced mechanical nociceptive hypersensitivity." (PMID 34549177, 2021). "It should be noted that the use of add-on therapy to insulin may indicate more severe diabetes or used to slow the progression of complications." (PMID 33947391, 2021). "Accumulating evidence links diabetes with severity of AP, suggesting that endogenous insulin may be protective." (PMID 34282152, 2021). "Our findings of patients with lower BMI and WC having reduced insulin levels would also enable clinicians to be more selective in requesting expensive tests for the individuals with newly diagnosed diabetes due to ID states such as slowly progressive type 1 DM (T1DM)." (PMID 33788827, 2021). "In fact, a four-day Intralipid infusion in volunteers with a family history of diabetes decreased the first and second phases of insulin secretion during a hyperglycemic clamp and during a mixed meal test, while it increased in healthy subjects without family history of diabetes." (PMID 33320449, 2021). "Therefore, controlling diabetes (diet, insulin, plaque stabilization with statins, etc.)was important to reduce the incidence of stroke in patients who underwent TEVAR." (PMID 35083299, 2021). "The most commonly reported method of managing diabetes was the use of oral medications, which were utilized by three-quarters of the clients, although approximately one-third of the clients used injectable agents (including insulin)." (PMID 34243783, 2021). "For example, those who had diabetes needed insulin injection." (PMID 34415236, 2021). "In the years before diabetes onset, insulin secretion increases and then decreases." (PMID 34206745, 2021). "However, plasma insulin levels are usually measured for diabetes mellitus, which are unsuitable for the general population." (PMID 33816569, 2021). "Hypoglycaemia (blood glucose concentration below the normal range) has been recognised as a complication of insulin treatment from the very first days of the discovery of insulin, and remains a major concern for people with diabetes, their families and healthcare professionals today." (PMID 33550443, 2021). "She did not have diabetes and had no access to oral hypoglycemic agents, insulin, or any other drug known to cause hypoglycemia." (PMID 34430127, 2021). "Diabetes is a group of metabolic disorders, which results from insufficient functional pancreatic β-cell mass either due to the autoimmune destruction of insulin producing β-cells, or their death or de-differentiation as compensation for insulin resistance." (PMID 34062490, 2021). "The GBD study included ‘cases of diabetes that are on insulin’ and could thus include people with type 2 diabetes or gestational diabetes in addition to type 1 diabetes." (PMID 34599655, 2021). "Finally, Frederick Banting, John MacLeod, Charles Best and J.B. Collip (1921/1922) succeeded in preparing insulin capable of efficiently treating a young boy with diabetes." (PMID 33430527, 2021).